IL6 (interleukin 6)
Diseases named in the same sentence as IL6 in open-access papers (continued):
Sharing a sentence is not in itself a finding about the gene and the disease.
Stroke (continued). "Stroke patients were found to have significantly higher levels of serum IL-6 (stroke: 6.26 ± 9.23 pg/ml, control: 1.96 ± 3.77 pg/ml, p=0.0014) and IL-8 (stroke: 7.27 ± 36.53 pg/ml, control: 3.15 ± 2.47 pg/ml, p=0.0017) compared to controls." (PMID 31927534, 2020). "Using quantitative reverse transcription-PCR, we confirmed increased mRNA expression of LCN2 as well as anti-inflammatory cytokines-Arg1, IL-10, and decreased mRNA level of pro-inflammatory cytokines-IL-6, IL-23 in the tumor of cancer-bearing stroke mice." (PMID 32153594, 2020). "Cytokine-based multimarker score composed of ex vivo released IL-12, IL-10, TNFα, and plasma IL-6 adds prognostic value to clinical model for predicting stroke outcome." (PMID 31906994, 2020). "We found that the serum levels of sTREM-1, TNFα, IL-6, and S100B were correlated with the severity of stroke, as evaluated by TOAST and NIHSS after acute ischemic stroke." (PMID 33375339, 2020). "We explored an association between ex vivo cytokine release, circulating interleukin (IL)-6 as a marker of systemic inflammation, and stroke prognosis." (PMID 31906994, 2020). "CSF IL-6 is elevated within 24 hours in stroke patients and elevated in serum and plasma during the first week after stroke." (PMID 32244523, 2020). "One of the most studied cytokines in the cerebrospinal fluid and blood of stroke patients is the proinflammatory IL-6." (PMID 33076354, 2020). "Microglia activation towards M1 phenotype augments post-stroke neuroinflammation and decreases neurogenesis by secreting pro‐inflammatory factors IL‐1, IL‐6, IL‐12, and nitric oxide." (PMID 32818074, 2020). "Through metabolic syndrome conditions, higher levels of IL-6 have been linked with cardiovascular diseases, being people with the highest level of IL-6 twice to five times more likely to have a heart attack, stroke, or another cardiovascular episode." (PMID 32708089, 2020). "It has been described that during the first hours after stroke, pro-inflammatory cytokines are up-regulated (IL-6, IL-1, TNFα, IL-8, MCP-1, etc)." (PMID 32111174, 2020). "IL-6 is a pro-inflammatory cytokine that is elevated in blood plasma and the brain at 3–24 h following experimental stroke." (PMID 32872405, 2020). "In contrast only IL-1 α and IL-6 were upregulated in the side of the brain corresponding to the transient occlusion at this timepoint after DCAL stroke." (PMID 33097782, 2020). "Most of the laboratory tests except for IL-6 and procalcitonin appeared to be useful for indicating the presence of inflammation and the prothrombotic state as a predictor for stroke, although results varied between the studies." (PMID 33123082, 2020). "IL-6 (Il6) and IL-1β (Il1b) are two crucial pro-inflammatory cytokines in experimental and human stroke." (PMID 33246465, 2020). "This association was independent of not only age and stroke severity, which are the most important stroke prognosticators, but also from circulating IL-6, a marker of systemic inflammation, and ex vivo release of TNFα, a marker of immunodepression." (PMID 32107751, 2020). "In particular, the group of strokes classified as CEI presented relevantly elevated plasma concentrations TNF-α, IL-6, and IL-1 in comparison with the other strokes." (PMID 32899616, 2020). "The mRNA levels of proinflammatory factors, including tumor necrosis factor-α (TNF-α), interleukin-1β (IL-1β) and interleukin-6 (IL-6) were significantly increased 1 to 7 days after stroke." (PMID 32010477, 2020). "The authors reported that proinflammatory IL-6 measured 12 h after the onset of cerebral ischemia has risen in stroke patients relative to controls; this increase was correlated with more severe neurological symptomatology and worse outcome." (PMID 32899616, 2020). "The analysis of sex-specific DEGs from GEO human blood samples showed not only specific but also opposite DEG alterations in females and males such as IL6, in the stroke genome-wide dataset." (PMID 31899762, 2020).
Stroke (continued). "LPS stimulation significantly increased the levels of pro-inflammatory markers, including IL-6, iNOS, and TNFα, which are reported to exacerbate brain damage during stroke." (PMID 32489699, 2020). "In support of this, social isolation after stroke impairs the transcriptional upregulation of interleukin-6 (IL-6) in the brain." (PMID 33193727, 2020). "IL‐6 and the size of the ischemic region were revealed to be independent predictors of premature stroke short‐term outcomes following premature stroke in young adults." (PMID 32583980, 2020). "In line with the elevation in H2R expression, we found elevated IL-6 expression levels in the gut mucosa after stroke only in Ag mice." (PMID 32429999, 2020). "In aged mice however, a significant increase in plasma IL-6 levels observed at 6 h persisted up to 24 h after stroke, when compared to age-matched shams." (PMID 32429999, 2020). "It is known that TNF-α, Il-1, and Il-6 increase in amount, even 40–60 times, within 24 h after a stroke." (PMID 33076354, 2020). "Data analysis revealed that the mean IL‐6 values were significantly higher in patients who had died following the stroke." (PMID 32583980, 2020). "Cocultures with stroke-Mo and MSCs showed a significant increase in IL-6 secretion when they were exposed to captopril." (PMID 32802081, 2020). "Numerous studies showed that elevated blood level of IL-6 is an independent predictor of poor functional outcome after stroke." (PMID 31906994, 2020). "NSE, IL-6, NT-proBNP, S-100b, hsCRP levels, and hsTroponin showed significantly lower circulating levels in stroke patients with previous TIA ≤ 24 h." (PMID 33192985, 2020). "IL-6 is a proinflammatory cytokine and plays a key role in the pathogenesis of stroke because of its ability to play a dual role." (PMID 32802081, 2020). "In young mice, we found increased levels of plasma IL-6 at 6-h post-stroke that normalized by 24 h, when compared to age-matched shams." (PMID 32429999, 2020). "Cluster analysis revealed interactions between synthesized cytokines, plasma IL-6, and stroke outcome." (PMID 31906994, 2020). "Elevated levels of circulating IL-6 and CRP as well as reduced TNFα production ex vivo are associated with poor outcome after stroke." (PMID 32107751, 2020). "The serum levels of sTREM-1, TNFα, IL-6, and S100B were correlated with the stroke volume and NIHSS, after acute ischemic stroke." (PMID 33375339, 2020). "It is known that there is a positive correlation between inflammatory cytokines (TNF-α, IL-1β, IL-6, etc.)and microglial activity after stroke." (PMID 32922507, 2020). "The results demonstrated that proinflammatory cytokines TNF-α (p < 0.05), IL-6 (p < 0.001), IL-1β (p < 0.01), IL-17 (p < 0.01), and IL-18 (p < 0.01) were increased in wild-type mice subjected to stroke." (PMID 32450881, 2020). "Although IL-6 and IL-1β have been reported to be neuro reparative after stroke by promotes post-stroke angiogenesis and reduce glutamate mediated excitotoxic cell death, their neurodestructive roles are widely demonstrated." (PMID 32010477, 2020). "More severe strokes in the AIS + D group compared to the AIS group have greater potential to contribute to the observed elevations of serum IL-6 and CRP in the former group, as both IL-6 and CRP in blood are elevated by ischemic stroke." (PMID 32758167, 2020). "By two-way ANOVA, there was a significant stroke effect on serum IL-6 levels (p = <0.0001) in both young and aged animals." (PMID 31927534, 2020). "IL-6 and the IL-6 receptors promote chronic inflammation in the CNS and lead to the progression of PD, AD, stroke, and other nervous system diseases." (PMID 33328961, 2020). "A significant age effect (p = <0.0001) and an interaction effect of age/stroke (p=0.0005) was also seen, driven by the augmented increase in IL-6 after stroke in aged animals (p=<0.0001) compared to young animals." (PMID 31927534, 2020).
Stroke (continued). "Captopril also increased IL-6 secretion from cocultures of stroke-Mo and MSCs indicating a strong proinflammatory effect on MSCs and their interaction with Mo." (PMID 32802081, 2020). "This demonstrates how meningeal MC-derived IL-6 can, in part, explain the MC-dependent effects in stroke pathology." (PMID 31001088, 2019). "To evaluate the inflammatory responses of BDMP injection and Lactadherin treatment in stroke mice, we measured the expression of leukocytes, microglia/macrophages, neutrophils, IL1β, IL6, and TNFα in the cortex and striatum of IBZ." (PMID 31993045, 2019). "We also investigated the roles of IL-6-mediated balance of cell-mediated immunity in the promoting effects of hyperforin in post-stroke neuroangiogenesis." (PMID 31133816, 2019). "In the initial phase after stroke, interleukin-6 (IL-6) appears in the damaged brain tissue and its elevated level is observed up to 12 months after ischemia." (PMID 31514749, 2019). "Under normal conditions, IL-6 expression is low in the brain, but it increases largely in neurological diseases such as stroke, brain damage and seizures." (PMID 31297084, 2019). "In animal models of stroke and in humans, IL-6 is increased in serum and cerebrospinal fluid (CSF) after stroke." (PMID 31096580, 2019). "The number of BrdU+/CD31+ cells in the ischemic penumbra of hyperforin-treated mice at 28 dpi was significantly decreased after anti-IL-6 intervention (7 ± 1 vs. 4 ± 1, P < 0.05), indicating hyperforin increases post-stroke angiogenesis via IL-6." (PMID 31133816, 2019). "For example, how does the meningeal MC-derived IL-6 execute its function to exacerbate stroke pathology?" (PMID 31001088, 2019). "In contrast to TNFα and IL-1β, IL-6 mainly has neuroprotective effects and plays a major role in body temperature regulation in stroke patients." (PMID 31544811, 2019). "We hypothesized that serum concentrations of interleukin-6 (IL6) and lipoprotein-associated phospholipase A2 (LpPLA2) were inversely associated with long-term functional decline independently of vascular risk factors, stroke and myocardial infarction (MI) occurring during follow-up." (PMID 30934019, 2019). "In the present study, we further confirmed the promoting role of astrocytes-derived IL-6 in post-stroke neuroangiogenesis and functional recovery." (PMID 31133816, 2019). "Previous studies reported that circulating IL-6 was closely correlated with brain infarct volume or stroke severity, although contradicting results were reported." (PMID 31164999, 2019). "Immunomodulatory properties of intra-arterially transplanted MSCs were demonstrated in the rat brain injured by stroke, where a statistically significant decrease in IL-2 mRNA and IL-6 mRNA levels was observed." (PMID 31514749, 2019). "Perivascular macrophages and microglia play an important role in the stroke-induced inflammatory response via production of proinflammatory cytokines (IL1|upbeta TNFα IL6, IL12) and ROS." (PMID 31543756, 2019). "As compared to the vehicle-treated stroke animals, IL-6 expression levels were markedly upregulated in the PI samples from the animals treated with IL-13 (p = 0.0055)." (PMID 31372938, 2019). "Our previous studies found that astrocytes-derived IL-6 is essential to post-stroke angiogenesis and neurogenesis mediated by enriched environment and social support." (PMID 31133816, 2019). "Our previous study found that astrocytic IL-6 is essential for enriched environment-mediated promotion of post-stroke angiogenesis and functional recovery." (PMID 31133816, 2019). "The present investigation demonstrated that moderate-intensity ET significantly decreased plasma MPO and IL-6 levels, inflammatory cytokines, in stroke patients." (PMID 31835774, 2019). "In the present study, 4 weeks of ET enhanced platelet mitochondrial OXPHOS and ETC capacities by increasing Complex II activity, but lowered plasma MPO and IL-6 concentrations in the stroke patients." (PMID 31835774, 2019).
Stroke (continued). "Given that IL-6 is critical to post-stroke angiogenesis and long-term functional recovery, we performed double immunofluorescence labeling to identify the cellular source of IL-6 at 28 dpi." (PMID 31133816, 2019). "The three major proinflammatory cytokines are interleukin 1β (IL-1β), tumor necrosis factor-alpha (TNF-α), and interleukin-6 (IL-6) that provoke and aggravate an inflammatory response after stroke." (PMID 31291966, 2019). "Our studies indicate that the levels of two major pro-inflammatory cytokines associated with stroke injury, TNF-α and IL-6, were elevated following MCAO injury." (PMID 31354401, 2019). "Alveolar macrophages and epithelial and endothelial cells of Sham and Stroke animals were also isolated for evaluation of mRNA expression of interleukin (IL)-6 and tumor necrosis factor (TNF)-α." (PMID 30290827, 2018). "Stroke-induced monocyte dysfunction resulted in an increase of the interleukin-10 (IL-10) level as well as a decrease of the interleukin-6 (IL-6), tumor necrosis factor-α (TNF-α) and interleukin-1β (IL-1β) levels." (PMID 29636059, 2018). "Reduced ex vivo release of pro-inflammatory cytokines after LPS stimulation and the elevated plasma IL-6 are signatures of post-stroke delirium." (PMID 29669581, 2018). "The association of LDL cholesterol, homocysteine, hypertension, history of stroke, depressive symptoms, interleukin-6, a1-antichymotrypsin, alcohol use and smoking with cognitive decline significantly differed between the age groups." (PMID 30126373, 2018). "This study showed that the association of LDL cholesterol, homocysteine, hypertension, history of stroke, depressive symptoms, IL-6, ACT, alcohol use and smoking with cognitive decline was age-dependent." (PMID 30126373, 2018). "Adipose tissue secretes many types of adipokines (such as leptin, interleukin 6, and adiponectin) that play a role in the progression of stroke." (PMID 30038059, 2018). "In this study, the anti-inflammatory drug (canakinumab) in 150-mg and 300 mg doses, four times a year, achieved a 40% relative risk reduction (RRR) in plasma CRP and IL-6 levels, in addition to a 15% RRR in the incidence of MI, stroke, or CV death." (PMID 29644229, 2018). "Gene expression of IL-6 was higher in alveolar macrophages and endothelial cells from Stroke animals compared to Sham animals." (PMID 30290827, 2018). "In conclusion, reduced ex vivo release of pro-inflammatory cytokines after LPS stimulation and elevated plasma IL-6 are signatures of post-stroke delirium." (PMID 29669581, 2018). "Increased plasma and cerebrospinal fluid levels of IL-6 seem to be correlated with stroke severity and poor clinical outcome in stroke patients." (PMID 29452577, 2018). "In stroke patients, a source of circulating IL-6 seems to be an ischemic brain or an adipose tissue." (PMID 29669581, 2018). "Inflammatory cytokines such as TNF-α, IL-1β, and IL-6 play a role in the induction and pathoprogression of stroke." (PMID 30046341, 2018). "The associations of LDL cholesterol, homocysteine, hypertension, history of stroke, depressive symptoms, IL-6, ACT, alcohol use and smoking with cognitive decline were different per age group." (PMID 30126373, 2018). "Unstimulated macrophages isolated from naïve rats only upregulated expression of TNF-α and IL-6 following exposure to serum from Stroke rats." (PMID 30290827, 2018). "Serum inflammatory factors interleukin-1-α and interleukin-6 increased after stroke in all groups, compared to the sham group in which this rise was significant in IL-1α." (PMID 30719249, 2018). "L-902,688 further reduced acute phase IL-6 expression, and increased IL-6 is correlated with larger stroke volume and worse outcome." (PMID 29527151, 2018). "STAT3, and IL6, have in a number of in vivo studies been suggested to precondition better recovery after stroke in mouse models." (PMID 29518129, 2018).
Stroke (continued). "Studies have shown that TNF-α, IL-1β, and IL-6 expression is elevated 0.5, 6, and 3.5 h after stroke, respectively." (PMID 30001721, 2018). "The astrocytic HMGB1/IL-6 signaling pathway participates in angiogenesis, neurogenesis, and the promotion of post-stroke functional recovery." (PMID 30197589, 2018). "The association of LDL cholesterol, homocysteine, hypertension, history of stroke, depressive symptoms, IL-6, ACT, alcohol use and smoking with cognitive decline differed between the age groups." (PMID 30126373, 2018). "At 24 h following stroke, IL-5 and IL-6 were increased in the infarct of the OPN-/- mice compared to the WT mice." (PMID 30417081, 2018). "In response to stroke, both obese ob/ob and control ob/– mice had significantly increased concentrations of plasma and liver IL-6, and plasma granulocyte-colony stimulating factor (G-CSF) and CXCL1." (PMID 28798136, 2017). "Functional assays showed that deficits in the pole test, rotarod test and EBST were worse after treatment with anti-IL-6 in enriched mice 3 and 4 weeks after stroke." (PMID 28845299, 2017). "In our investigation, results from tumor necrosis factor (TNF-α), interleukin 1 beta (IL-1β) and interleukin 6 (IL-6) assessment demonstrated that of Danshensu or HSYA treatment has an anti-inflammatory effect for stroke." (PMID 29383171, 2017). "In this study, our in vivo results showed that astrocytic HMGB1 played an essential role in the promoting effects of EE in the expression of IL-6 in the ischemic hemisphere during stroke recovery." (PMID 28845299, 2017). "Following stroke huge panoply of proinflammatory cytokines that are released in the bloodstream and detectable in the serum, besides IL-6 and TNF-α, also IL-10, IL-4, IL-17, IL-23, and TGF-β increase." (PMID 28373915, 2017). "IL-17A, produced mainly by activated Th17 cells, can induce the secretion of a variety of stroke-related cytokines, such as IL-6, TNF-α, IL-1β, CXCL1 and CXCL8." (PMID 29262579, 2017). "IL-6 has been detected in plasma and cerebrospinal fluid of stroke patients, and IL-6 immunoreactivity has been detected in microglia and cortical neurons of ischemic stroke models." (PMID 28936196, 2017). "Along similar lines, levels of interleukin-6, cortisol, and reactive oxygen species are all known to be elevated acutely in stroke pathology, and all have been shown to promote sCD163 production." (PMID 29021532, 2017). "In the process of stroke, I/R induced the production and secretion of apoptosis and such inflammation associated cytokines as TNF-α, IL-1β and IL-6." (PMID 29383171, 2017). "Stroke also resulted in an inflammatory response in the fat of obese mice characterised by increased IL-6, TNFα and ICAM-1 expression." (PMID 28798136, 2017). "PI3K/AKT signaling pathway was involved in HMGB1-induced IL-6 production from astrocytes in enriched mice during stroke recovery." (PMID 28845299, 2017). "Statistical evaluation revealed an independently positive correlation between lesion volume and CRP, IL-6, and IL-23 on day 3 after stroke onset (all p < 0.05)." (PMID 27682880, 2017). "In stroke patients, increased TLR-2 and TLR-4 expression on monocytes is associated with higher serum levels of TNF-α, IL-1β, and IL-6." (PMID 29054968, 2017). "Tumor necrosis factor, interleukin-1, and interleukin-6 are potent inflammatory cytokines that have been shown to modulate tissue injury in experimental stroke." (PMID 28109273, 2017). "In BALB/c mice at 7 weeks post-stroke, levels of G-CSF, IL-2, IL-6, IL-17, IP-10, MCP-1, and RANTES were increased, and levels of GM-CSF, IFNγ, IL-10 were decreased compared to sham mice." (PMID 27600707, 2016). "Arac described that interleukin 6 and chemokine (C-C motif) ligand 7, contributed to stroke pathology." (PMID 27213359, 2016). "Aged mice had elevated serum levels of IL-6 for 24 hours following stroke, when levels had returned to baseline in young mice." (PMID 27115295, 2016).